IL3 (interleukin 3)
Diseases named in the same sentence as IL3 in open-access papers (continued):
Sharing a sentence is not in itself a finding about the gene and the disease.
endometriosis (1 paper, 2021). The growth of functional endometrial tissue in anatomic sites outside the uterine body. "The mean concentration of IL-3 in the women with endometriosis was 125.9 ± 79.8 pg/ml, which was much lower than the control group (173.9 ± 109.2 pg/ml, p = 0.04)." (PMID 35571503, 2021). "Using ROC curve analysis in the diagnosis of endometriosis, the area under the curve (AUC) for IL-3 was 0.635 (95% CI: 0.50-0.76), and the sensitivity and specificity were 58% and 60%, respectively." (PMID 35571503, 2021). "Table III shows the AUC, sensitivity, and specificity of IL-3, IL-5, and IL-6 for diagnosis of endometriosis with confidence intervals." (PMID 35571503, 2021). "The results demonstrated significant alterations in the FF concentration of IL-6 and IL-3 in endometriosis women compared to the controls." (PMID 35571503, 2021). "The current study displayed a lower concentration of IL-3 as an anti-inflammatory cytokine in the FF samples of women with endometriosis, suggesting the role of IL-3 in the pathogenesis and progression of this chronic inflammatory condition." (PMID 35571503, 2021). "In this study, IL-3, IL-5, and IL-6 were measured in the FF of women with endometriosis." (PMID 35571503, 2021). "IL-3 and IL-6 were significantly changed in the FF of the women with endometriosis compared with the control group (p = 0.04, and p < 0.01, respectively), and the mean concentration of IL-5 in the endometriosis group was lower than in the control group (p = 0.5), but this was not significant." (PMID 35571503, 2021). "In summary, the results demonstrated a significant elevation in the IL-6 concentration and a remarkable reduction in the IL-3 levels in the FF samples of women with endometriosis compared to the control group, suggesting the involvement of these cytokines in the pathogenesis of endometriosis." (PMID 35571503, 2021). "This study aims to investigate follicular fluid (FF) concentration of interleukin (IL)-3, IL-5, and IL-6 in women with and without endometriosis." (PMID 35571503, 2021).
enteritis (1 paper, 2022). Inflammation of the small intestine. "In addition to increased MC numbers and increased expression of MC proteases, we found an increased expression of the receptor for the murine MC growth factor IL-3 in OVA-induced enteritis." (PMID 35163137, 2022).
Fanconi anemia (1 paper, 2021). Fanconi anemia (FA) is a hereditary DNA repair disorder characterized by progressive pancytopenia with bone marrow failure, variable congenital malformations and predisposition to develop hematological or solid tumors. "A study in AML provided evidence that CD123 positive cells isolated from Fanconi anemia patients with AML exhibited increased IL-3 responsiveness." (PMID 33796456, 2021).
fibroids (1 paper, 2024). "Lachnospiraceae UBA629A, which was depleted in patients with CPP and enriched in patients with fibroids, was negatively correlated to IL-3 (p < 0.05) and IL-1Ra (p < 0.05)." (PMID 38972981, 2024).
fibrosis (1 paper, 2026). the formation of excess fibrous connective tissue in an organ or tissue in a reparative or reactive process. "Moreover, IL-3 production by memory CD4+ T cells was essential for aggravation of fibrosis in memory situations." (PMID 41837289, 2026).
filariasis (1 paper, 2020). "The family of let-7 miRNAs has been identified in Brugia pahangi, the causative agent of zoonotic filariasis, and the upregulation of several let-7 genes seems to correlate with the development of iL3 following host infection." (PMID 32641726, 2020).
glaucoma (1 paper, 2022). Increased pressure in the eyeball due to obstruction of the outflow of aqueous humor. "Among the genes that were downregulated with the polyherbal and were related to the development of glaucoma are BMP2 and IL3, identified by bioinformatics analysis." (PMID 35625159, 2022).
Headache (1 paper, 2026). Cephalgia, or pain sensed in various parts of the head, not confined to the area of distribution of any nerve. "Using the ABplex Multi-Metric Streaming Joint Analysis to detect inflammatory factors, we observed significantly elevated levels of IL-3 in cerebrospinal fluid, but not in blood samples, of patients with headaches and TBI." (PMID 41915872, 2026).
hemorrhagic fever (1 paper, 2017). An infectious disease caused by certain viruses or bacteria that can damage the walls of tiny blood vessels, making them leak, and can hamper the blood's ability to clot and cause severe, life-threatening illness. "Hemorrhagic fever with renal syndrome cases were characterized by a strong expression of MIF, IL-12p40, IL-3, IL-16, CXCL9, CCL27, CXCL1, and HGF." (PMID 28572804, 2017).
hookworm infections (1 paper, 2020). "Our data suggest that canonical dauer pathways indeed regulate iL3 activation in the hookworm N. brasiliensis and that DAF-12 may be a therapeutic target in hookworm infections." (PMID 32238181, 2020).
hyperreactivity (1 paper, 2022). "On the contrary, another OVA model showed reduced levels of eosinophils and bronchial hyperreactivity, when administering anti-IL-3 on the last day of the protocol, after the challenge." (PMID 35281014, 2022).
invasive breast carcinoma (1 paper, 2015). A carcinoma that infiltrates the breast parenchyma. "Given the importance of IL-3 in augmenting immune responses, it is possible that its down-regulation in malignant seromas might reflect a mechanism by which invasive breast cancers escape immune surveillance." (PMID 26361584, 2015).
ischemic cardiomyopathy (1 paper, 2019). Ischemic cardiomyopathy is a cardiomyopathy in which a weakness in the muscle of the heart due to inadequate oxygen delivery to the myocardium with coronary artery disease being the most common cause. "Interleukin-3 has demonstrated improvement in left ventricular function and survival in animal models with acute MI or ischemic cardiomyopathy." (PMID 32064466, 2019).
keloid (1 paper, 2023). An irregularly shaped, elevated mark on the skin caused by deposits of excessive amounts of collagen during wound healing. "In addition, many cytokines, such as TGF-β, IL-3, IL-6, and IL-14, are also important factors in promoting keloid formation." (PMID 37895153, 2023).
leukopenia (1 paper, 2021). "Is adding CHM on top of conventional care (granulocyte colony‐stimulating factor (G‐CSF)/granulocyte‐macrophage colony‐stimulating factor (GM‐CSF)/interleukin‐3 (IL‐3)) more effective in improving leukopenia among adult patients receiving cancer palliative care?" (PMID 34107142, 2021).
Lyme borreliosis (1 paper, 2025). "The tick-related disorder Lyme borreliosis was chosen as the disease model; tick bites are associated with cutaneous IL-3-mediated basophil recruitment." (PMID 41470158, 2025).
lymphopenia (1 paper, 2022). Reduction in the number of lymphocytes. "Steroid‐induced lymphopenia occurs via inhibition of T‐cell activation by inhibition of IL‐2, IL3, IL‐4, and IL‐6,43 and suppression of dendritic cell maturation and function." (PMID 35478442, 2022).
magnesium deficiency (1 paper, 2022). A nutritional condition produced by a deficiency of magnesium in the diet, characterized by anorexia, nausea, vomiting, lethargy, and weakness. "In contrast, and at variance with our previous finding that expression of cytokine proteins such as IL-8, MCP-1, GRO, GROα, IL-2 and IL-3 was enhanced with magnesium deficiency, the array analysis found little impact of low magnesium on interleukins and their associated signaling pathway." (PMID 36079843, 2022).
megakaryoblastic leukemia (1 paper, 2021). "MBA2 cell line (secreting interleukin-3 (IL-3)) and the human megakaryoblastic leukemia cell line, M07e (depending on IL-3 for proliferation and survival), were co-encapsulated within agarose hydrogel droplets at different ratios." (PMID 35479393, 2021).
mood disorder (1 paper, 2023). A cognitive disorder a disturbance in which the person's mood is hypothesized to be the main underlying feature. "Abnormal serum levels of IL-3 have been observed in patients with mood disorders." (PMID 37957650, 2023). "Furthermore, according to previous studies, IL-3 and IL-3R are expressed in the brain cells of patients with mood disorders." (PMID 37957650, 2023).
myeloid malignancies (1 paper, 2019). "A genetically engineered diphtheria toxin fused with interleukin-3 (SL-401 or tagraxofusp) has shown robust activity in blastic plasmacytoid dendritic cell neoplasm and promising response rates in different myeloid malignancies, including eradication of minimal residual disease." (PMID 30621282, 2019).
nasal polyp (1 paper, 2019). "We also showed in the same year that nasal polyp eosinophils in tissue have a longer survival time compared to blood eosinophils and that anti-IL-5, but not anti-IL-3 or anti-GM-CSF could induce apoptosis in tissue eosinophils, being confirmed in human disease today." (PMID 31452831, 2019).
nematode infection (1 paper, 2020). "Upon adoptive transfer, T cell-derived IL-3 also induced basophilia in nematode infection model." (PMID 31941161, 2020).
neuritis (1 paper, 2025). A neuropathy arising from inflammation of one or more nerves. "Inflammatory proteins, such as CNPY2 (neuritis marker) and IL3 (CH3L1), a preinflammatory factor and tumor marker, were also more prevalent, along with immune and wound healing modulators CP4F3 (cytochrome P450) and FKB1A (TGF‐B receptor blocker), which regulate inflammation and immune responses." (PMID 40457720, 2025).
non-small cell lung carcinoma (1 paper, 2024). A group of at least three distinct histological types of lung cancer, including non-small cell squamous cell carcinoma, adenocarcinoma, and large cell carcinoma. "Furthermore, serum IL-3 is elevated in various cancers, including colorectal, pancreatic and non-small cell lung cancer." (PMID 38903497, 2024).
oral cancer (1 paper, 2020). "We herein show presence of IL-3 in oral epithelial cells under the effect of WPS, thus indicating its role in oral cancer progression." (PMID 32961854, 2020).
osteosarcoma (1 paper, 2009). A usually aggressive malignant bone-forming mesenchymal neoplasm, predominantly affecting adolescents and young adults. "For example, in both interleukin-3 (IL-3)-dependent 32D.3 myeloid progenitors and U2OS osteosarcoma cells, the non-HLH region of Id2 performed a prominent apoptosis-promoting function." (PMID 19257909, 2009).
pancreatic ductal adenocarcinoma (1 paper, 2022). An infiltrating adenocarcinoma that arises from the epithelial cells of the pancreas. "For example, MCP3/CCL7, IL4 and IL3 have been previously shown to be involved in the tumour microenvironment of pancreatic ductal adenocarcinoma and play a complex role in the regulation of tumour-promoting inflammation." (PMID 35064782, 2022).
Pancytopenia (1 paper, 2025). An abnormal reduction in numbers of all blood cell types (red blood cells, white blood cells, and platelets). "It has been previously shown that G-CSF, granulocyte-monocyte colony-stimulating factor (GMCSF), pegylated G-CSF (pegfilgrastim), interleukin-11, interleukin-3, and erythropoietin have regenerative effects on pancytopenia." (PMID 40429945, 2025).
plasmacytoma (1 paper, 2016). Plasmacytoma is a localized mass of neoplastic monoclonal plasma cells that represents approximately 5% of all plasma cell neoplasms. "In the present studies, untreated K14E7 Fancd2−/− marrow in LTBMC and subcultured nonadherent cells grown in the presence of IL-3 spontaneously transformed to malignant plasmacytoma cell lines." (PMID 27637088, 2016). "Furthermore, cytokeratin 14 and E7 were expressed in cultured K14E7 Fancd2−/− marrow and nonadherent cells subcultured in Interleukin-3 (IL-3) generated factor-independent (FI) malignant plasmacytoma cell lines." (PMID 27637088, 2016).
Pleural effusion (1 paper, 2022). The presence of an excessive amount of fluid in the pleural cavity. "Based on our retrospective study, we selected four different TNBC cell lines (two originated from pleural effusion and two from primary tumours) to evaluate whether the activation of the IL-3/IL-3Rα axis impacts TNBC aggressiveness." (PMID 36010912, 2022).
prediabetes (1 paper, 2016). "The expression of IL-3 was also elevated 2.4413-fold in prediabetes patients which is less than its overexpression in T2DM patients (176.599-fold)." (PMID 27781209, 2016). "Though we do not have any convincing reason for this lower expression of IL-3 in prediabetes patients." (PMID 27781209, 2016).
prostate tumor (1 paper, 2013). "This study aimed to evaluate whether co-expression of interleukin-3 (IL-3) could enhance the anti-tumor activity of HSV-sr39tk/GCV prodrug gene therapy using a murine TRAMP-C1 prostate tumor model." (PMID 23441198, 2013).
rectal cancer (1 paper, 2014). A primary or metastatic malignant neoplasm that affects the rectum. "Several cytokines, including interleukins and interferons, and other mediators of inflammation were associated with both colon (INFGR1, IL6, IRF2, NFκB1A, TLR2) and rectal cancer survival (IL1A and IL3), as was suppressor of cytokine signaling (SOCS1)." (PMID 25541970, 2014).
retinal detachment (1 paper, 2011). An eye emergency condition which may lead to blindness if left untreated. "Since microglial cells have also been shown to express IL-3, its cellular source and function after retinal detachment remain unknown." (PMID 21556354, 2011).
retinal ischemia (1 paper, 2021). A ischemic disease that involves the retina. "As in whole blood, it has been shown that caffeine does not change the LPS-induced secretion of IL-10, IL-6, and IL-1β, while reduced mRNA expression of IL-6, IL-12, and IL-3 has been found in LPS-activated RAW264.7 cells or retinal ischemia/reperfusion-induced IL-6 and IL-1β secretion by microglia." (PMID 34371919, 2021).
RSV bronchiolitis (1 paper, 2021). "The serum level of IL-3, IL-4, IL-10, and IL-13, which originate from Th2 cytokine, were higher in children with RSV bronchiolitis secondary wheezing, and IL-3 can be used as a predictor of recurrent wheezing." (PMID 33691633, 2021).
Salmonella Infections (1 paper, 2010). Infections with bacteria of the genus SALMONELLA. "Accordingly, we also observed that Interleukin-3 and 22 were up-regulated in mouse colon mucosa with Salmonella infection at four days." (PMID 21172007, 2010).
septic shock (1 paper, 2024). Shock caused by infection; frequently caused by gram negative bacteria, although some cases have been caused by other bacteria, viruses, fungi, and protozoa; characterized by fever, chills, tachycardia, tachypnea, and hypotension. "First, in septic shock, a secondary analysis of the Vasopressin and Septic Shock trial suggested that higher baseline levels of IL-3, IL-6, and CCL4 may identify patients as potential responders to glucocorticoids resulting in reduced mortality." (PMID 38441708, 2024).
severe congenital neutropenia (1 paper, 2025). "IL3 increases the absolute neutrophil count and is associated with severe congenital neutropenia (SCN)." (PMID 39776289, 2025).
small cell lung carcinoma (1 paper, 2023). Small cell lung cancer (SCLC) is a highly aggressive malignant neoplasm, accounting for 10-15% of lung cancer cases, characterized byrapid growth, and early metastasis. "Human interleukin-3 (IL-3) assesses the tolerance, hematologic effects, and safety in individuals with small-cell lung cancer (SCLC) before and following multi-agent antineoplastic therapy in a randomized, placebo-controlled, double-blind study." (PMID 36874133, 2023).
squamous cell cervical cancer (1 paper, 2020). "CSF2RB is the common beta chain receptor for the GM-CSF, IL-3, and IL-5 activation and a rare genetic variant of CSF2RB (rs16997517) is related to a decreased risk of squamous cell cervical cancer." (PMID 33042828, 2020).
systemic sclerosis (1 paper, 2026). A chronic disorder, possibly autoimmune, marked by excessive production of collagen which results in hardening and thickening of body tissues. "In patients with systemic sclerosis, IL-3 expression by T cells was markedly increased, especially after a long disease duration accompanied by involvement of internal organs." (PMID 41837289, 2026).
tauopathy (1 paper, 2021). Neurodegenerative disorders involving deposition of abnormal tau protein isoforms (tau proteins) in neurons and glial cells in the brain. "Neuroinflammation play an important role in patient with AD and other primary tauopathy diseases as well as in animal models of tauopathy, featured by disease associated with microglia activation, reactive astrocytes, and activated cytokines such as complement C3 and interleukin-3." (PMID 35082657, 2021).
tick infestation (1 paper, 2017). Infestations with soft-bodied (Argasidae) or hard-bodied (Ixodidae) ticks. "We here demonstrate that skin CD4+ memory T cells play an essential role in acquired protective immunity against tick infestations through the production of interleukin-3 (IL-3) that in turn induces basophil recruitment to the tick re-infestation site." (PMID 29085376, 2017). "Skin CD4+ memory T cells play an essential role in acquired protective immunity to tick infestation through the production of IL-3 that in turn induces basophil recruitment to the site of tick re-infestation." (PMID 29085376, 2017).
trachoma (1 paper, 2009). "Risk effects estimated by OR (95%CI) for the association between extended and reduced haplotypes across IL3 and CSF2 and risk of scarring trachoma and trichiasis." (PMID 20015396, 2009).
trichomoniasis (1 paper, 2011). An infection that is caused by Trichomonas. "For exampleMIP-1α, VEGF and MPO levels were significantly different than controls inChlamydia and trichomoniasis but not BV while in contrast,IL-6, IL-10, GM-CSF, G-CSF, IL-3, IL-7 and IL-12 were significantly changed inChlamydia and BV but not trichomoniasis." (PMID 21572958, 2011). "Incontrast, IL-12, IL-7, IL-10, IL-3, and IL-4 were increased in BV when comparedto control samples but not in trichomoniasis." (PMID 21572958, 2011).
tuberculosis (1 paper, 2019). A chronic, recurrent infection caused by the bacterium Mycobacterium tuberculosis. "Although our own ongoing studies and limited reports indicate only a moderate role for IL-3 in murine models of tuberculosis and HSV, there are indications for other possible roles for IL-3–producing CD4+ T cells, including in contact hypersensitivity and antiparasite immunity." (PMID 31356170, 2019).
type 2 diabetes (1 paper, 2023). "Intriguingly, increased serum levels of IL-3 have recently been associated with the onset of type 2 diabetes in African American women as determined by serum levels of glucose and HbA1c." (PMID 38577257, 2023).
uveitis (1 paper, 2023). An inflammatory process affecting a part of or the entire uvea. "The production of inflammatory cytokines induced by HTLV-1-infected T cells, such as IL-1α, IL-2, IL-3, IL-8, IL-10, TFN-α and GM-CSF, produces an intraocular inflammatory environment in patients with uveitis." (PMID 37605273, 2023).
vasculitis (1 paper, 2012). "Plasma levels of IL-3 levels were normal in all vasculitis patient subgroups examined in this study." (PMID 22403660, 2012).